IL6 (interleukin 6)
Diseases named in the same sentence as IL6 in open-access papers (continued):
Sharing a sentence is not in itself a finding about the gene and the disease.
COVID-19 (continued). "This unique and inappropriate inflammatory response was observed, and it has been assumed that increased levels of IL-6 in COVID-19 patients would suppress interferon levels." (PMID 39126095, 2024). "The overproduction of IL-6 inhibits NK cell cytotoxicity, as confirmed by the in vivo treatment with therapeutic anti-IL-6R mAb, which increases NK cell function in COVID-19 patients." (PMID 38881905, 2024). "Studies have demonstrated that severe COVID-19 patients exhibit extremely high levels of proinflammatory cytokines like IL-6 and TNF-α, which contribute to chronic inflammation and oxidative stress." (PMID 39350850, 2024). "In severe COVID-19 patients, high level of IL-6 was produced in lung and acted on liver sinusoidal endothelial cells by IL-6 trans-signaling, inducing liver inflammation and even liver injury." (PMID 38890694, 2024). "All hematological inflammatory markers, including CRP (57.1%), ESR (40.7%), fibrinogen (54.5%), D-dimer (68.8%), PCT (66.7%), and IL-6 (60.7%), were elevated in approximately half of the patients in the COVID-19-related encephalitis group." (PMID 38772979, 2024). "COVID-19 disease severity was linked to multiple hematological markers (lymphopenia, thrombocytopenia, neutrophilia) and inflammatory markers (CRP, IL-6, ferritin), providing a rationale for research on PTX in COVID-19, as it affects many of those markers." (PMID 39446164, 2024). "This reaction involves the rapid release of high levels of proinflammatory cytokines, such as IL-6, TNF-α, and IL-1β, which are associated with various illnesses, including viral infections (e.g., COVID-19), autoimmune conditions, and sepsis." (PMID 39459194, 2024). "Despite these differences, higher concentrations of IFN-α2, IL-6, and IL-1, all of which are associated with HIV-related immune activation, differentially scaled with more severe COVID-19 in PLWH." (PMID 38368384, 2024). "Compared to standard care, remdesivir quickly improves low oxygen levels (reducing the need for ventilatory support) and reduces inflammation (lowering IL-6 levels), leading to a better course of moderate to severe COVID-19." (PMID 38610602, 2024). "Under the overdominant model analysis, we demonstrated that the IL-6 − 174 G/C genotype confers protection against the development of severe COVID-19 after adjusting for sex and age." (PMID 38783290, 2024). "In particular, we observed increase inthe levels of cytokines known to contribute to cytokine storms as IL-1β, IL-6, IL-12A, IL-12B, IFN-γ, and TNF-α as well as various chemokines and CSFs upon infection with the COVID-19 variants." (PMID 39759510, 2024). "Longitudinal serum cytokine analysis of 207 COVID-19 patients revealed that in early inflammatory responses, IL-6, TNF-α, IL-10, and IL-1β expression increased in those with severe disease." (PMID 38710800, 2024). "Some studies have shown that IL-6 maintains elevated levels in the peripheral blood of COVID-19 patients over long periods, possibly serving as a predictive biomarker for disease severity." (PMID 38165854, 2024). "Although our study has a limited number of cases, it underscores the importance of IL-6 as a predictor of COVID-19 disease severity." (PMID 39654886, 2024). "IL-6 is a central cytokine in the inflammatory response to COVID-19, playing both proinflammatory and anti-inflammatory roles that significantly impact disease progression." (PMID 39518964, 2024). "This release increases the systemic level of IL-6, IL-1b, TNF, and other proinflammatory cytokines, subsequently causing cytokine storm and a severe condition of COVID-19." (PMID 39640429, 2024). "A heatmap was constructed for joint analysis of the gene expression levels of cGAS and STING and plasma levels of IFN-α, TNF-α and IL-6 in acute COVID-19 and in the post-COVID-19 period." (PMID 38424312, 2024). "Interleukin-6 (IL-6) is particularly important in this cytokine release, with elevated levels serving as a marker of severe COVID-19." (PMID 39063569, 2024).
COVID-19 (continued). "It has been shown that certain cytokines, such as IL-6, IL-8, and G-CSF, exhibit significantly higher levels in severe COVID-19 cases, especially in patients requiring invasive mechanical ventilation." (PMID 39336857, 2024). "They demonstrated a significant decrease in miR-200c levels in COVID-19 patients hospitalized with an elevation of IL-6 amount, characteristic of an inflammatory state." (PMID 38549864, 2024). "For example, IL-6 inhibitor therapy with tocilizumab and sarilumab is being evaluated as a potential treatment for COVID-19." (PMID 38612744, 2024). "EGCG also can block the activation of NF-κB to controls the expression of many pro-inflammatory cytokines, including IL-1β, TNF-α, IL8, IL-6, all of which are induced in COVID-19." (PMID 38632501, 2024). "A recent study examined the potential connection between COVID-19 and periodontal disease, specifically through the role of IL-6." (PMID 38800223, 2024). "The principle for examining cytokine storm in COVID-19 includes a decline in blood lymphocyte count and elevated systematic inflammatory indicators, along with multiple cytokines, such as IL-1β, IL-6, and TNF-α." (PMID 37742314, 2024). "The same goes for COVID-19, where tocilizumab, an IL-6 antagonist, and baricitinib, a JAK inhibitor, have been found to lower mortality in selected groups of severely ill patients." (PMID 38985797, 2024). "The results presented here demonstrate that exposure of epithelial IB3-1 cells to the SARS-CoV-2 spike protein or COVID-19 BNT162b2 vaccine induces increased expression of NF-κB and increased expression of pro-inflammatory genes, particularly of IL-6 and IL-8." (PMID 39770027, 2024). "This genotype has been associated with lower levels of soluble IL-6 receptor, as well as a slight increment in plasmatic IL-6 in COVID-19." (PMID 39201427, 2024). "All of the CE species analyzed in our study cohort were negatively correlated with CRP, most of them with procalcitonin and some with IL-6 and ferritin in severe COVID-19." (PMID 39051245, 2024). "Another study, evaluating 79 markers in 35 COVID-19 patients, identified IL-6, Eotaxin, IL-8, IL-1Ra, and MCP-1 as the strongest mortality predictors." (PMID 39408907, 2024). "Another LC-MS/MS serum proteomics analysis determined the link between elevated IL-6 and the dysregulation of anti-microbial enzymes and coagulation factors in COVID-19 patients." (PMID 38672194, 2024). "In conclusion, this study validated the significant predictive value of PedPne scores, dNLR, and IL-6 in identifying and managing pediatric pneumonia post-COVID-19, with these tools demonstrating high specificity and sensitivity in clinical assessments." (PMID 39202577, 2024). "Elevated IL-6 levels have been observed in COVID-19 patients with pulmonary dysfunction, indicating cytokine-mediated pulmonary damage by SARS-CoV-2 viruses." (PMID 39594223, 2024). "IL-6 is a critical driver in the COVID-19 inflammatory state, and the inhibition is considered a potential treatment approach to prevent serious complications." (PMID 39640429, 2024). "Elevated IL-6 concentrations have been identified as an important predictor of mortality in COVID-19, as also shown in the present study." (PMID 39408907, 2024). "Levels of cytokines IL-1β, IL-6 and TNFα and levels of cortisol levels according to COVID-19/PASC status." (PMID 38348267, 2024). "In fact, these elevated systemic CD163 levels were correlated with proinflammatory cytokine release (particularly IL-6) in COVID-19-infected patients." (PMID 39334711, 2024). "The inflammatory storm in COVID-19 is driven by CD14+CD16+ monocytes expressing IL-6, as demonstrated in patients in intensive care units." (PMID 39125849, 2024). "A systematic review and meta-analysis showed that IL-6 and d-dimer levels were significantly elevated in patients with severe COVID-19." (PMID 39199353, 2024).
COVID-19 (continued). "We observed a positive correlation between bisected spike IgG abundances and IL-6 levels during acute moderate COVID-19 in adults." (PMID 39494457, 2024). "Among all individuals carrying TMPRSS2 rs2070788 genotypes, the IL-6 levels exhibited a significant elevation within the COVID-19 group when contrasted with the control group." (PMID 39188881, 2024). "In the first published study that addressed this issue during the COVID-19 pandemia, we showed the presence of an inverse relationship between serum [Na+] and IL-6 in a small cohort of COVID-19 patients." (PMID 39196447, 2024). "Characteristic is the paradigm of the cytokine release syndrome in COVID-19, for which several immunomodulatory drugs are under investigation or approved, such as tocilizumab (interleukin-6 (IL-6) receptor antagonist)." (PMID 39319267, 2024). "Serum levels of interleukin 6 (IL6) are elevated in inflammatory conditions and are associated with COVID-19 severity and the presence of respiratory complications." (PMID 38474287, 2024). "This study investigates the histological impact of nebulized tocilizumab—a monoclonal antibody targeting IL-6, traditionally administered intravenously for rheumatoid arthritis and severe COVID-19—on a murine model." (PMID 39065559, 2024). "Recent studies have confirmed the critical role of IL-6 and IL-10 in predicting severe outcomes in hospitalized COVID-19 patients, further validating our findings." (PMID 39203987, 2024). "IL-6, a vital pro-fibrotic inflammatory factor, was significantly elevated in the inflammatory factor storm of COVID-19 patients." (PMID 39444690, 2024). "Excessive IL6 is secreted by CD14+ and CD16+ monocytes during COVID-19 progression, which is associated with a systemic inflammatory reaction known as a cytokine storm." (PMID 39555074, 2024). "Elevated levels of bio-ADM and IL-6 are associated with AKI and critical illness in patients with COVID-19." (PMID 38336628, 2024). "In severe cases of COVID-19, elevated levels of IL-6 have been observed and are pointed out to contribute to the systemic inflammatory response and organ damage seen in some patients." (PMID 39359733, 2024). "Elevated PCT and IL-6 levels, in particular, have been previously identified as markers of severe COVID-19 outcomes, and their role in the coinfected population needs further exploration." (PMID 39768950, 2024). "In conclusion, M. cajuputi showed potential anti-inflammatory activity against COVID-19 by blocking IL-6 activity." (PMID 39640429, 2024). "IL-6 plays a critical role in the progression of COVID-19 and is responsible for the high mortality rate." (PMID 39118801, 2024). "The mean concentration of IL-6 in healthy individuals was 6.87 ± 4.23 pg/mL, whereas, in patients with severe COVID-19, it was significantly elevated at 28.10 ± 10.80 pg/mL, with a p-value of <0.001." (PMID 39407725, 2024). "In univariable analysis, we found that white blood cell, NLR, IL-6, CRP, LDH, D-dimer, PT level were all associated with COVID-19 elderly patients combined with respiratory failure." (PMID 39416623, 2024). "Using ROC analysis, we estimated a threshold for IL-6 and PCT levels above which the risk of hospitalization and severe or fatal outcome of COVID-19 increased." (PMID 38433829, 2024). "Myocarditis, which can arise as a result of COVID-19, is based on interleukin-6 (IL-6) stimulation and the resulting activation of a cytokine storm, in addition to direct damage to the heart." (PMID 39594168, 2024). "The abundance of both H. hathewayi and S. wiggsiae correlated with circulating inflammatory markers including IL-6, highlighting the possible role of the microbiome in COVID-19 severity and providing potential therapeutic targets for managing COVID-19." (PMID 39345212, 2024).
COVID-19 (continued). "This has also been shown in direct in vitro assays—with application of serum from COVID-19 patients with delirium with elevated IL-6 leading to decreased proliferation and increased apoptosis of a human hippocampal progenitor cell line." (PMID 39474424, 2024). "High IL-6 levels are known to predict worse outcomes in COVID-19 and contribute to the unique pattern of immune dysregulation seen in severe cases." (PMID 39272832, 2024). "A venous blood sample from 67 COVID-19 patients was used to measure IL-6 levels using the chemiluminescence assay." (PMID 39126095, 2024). "We investigated the association between baseline level of IL-6 and development of ACS in COVID-19 patients." (PMID 39395941, 2024). "IL-6 levels were rising with increasing COVID-19 severity and recorded the lowest levels in the control group." (PMID 38703289, 2024). "The characteristic increase in IL-6 during COVID-19 inhibits BMPR2, which normally protects against increased TGFβ signaling, and upregulated TGFβ1 contributes to hyperglycemia." (PMID 38674024, 2024). "The study confirms that IL-1 inhibition significantly reduced mortality in COVID-19 patients compared to IL-6 inhibition." (PMID 38392902, 2024). "Studies show thatpatients with COVID-19 have increased levels of cytokines such as interleukin-6(IL-6), which can lead to testicular dysfunction and worsen sperm quality." (PMID 39254469, 2024). "Numerous studies indicate that cytokine storm, characterized by high levels of inflammatory cytokines, including IL-6, is a contributing factor in the progression and severity of COVID-19." (PMID 38355623, 2024). "Differently from the previous inflammatory markers, IL-6 displays a significative difference between the two groups of patients, showing a very significative higher level in COVID-19-positive patients at T0." (PMID 39582872, 2024). "Specifically, IL-1β, TNF-α and IL-6, all of which are elevated in COVID-19, are potent activators of the p38 MAPK signalling cascade, which itself leads to further production of these cytokines." (PMID 39051370, 2024). "Studies conducted on individuals recovering from COVID-19, 3–5 and 8 months post-infection, have shown sustained high levels of IL-6 and two further anti-viral cytokines (IFN-β and IFN-λ1), which were associated with persistent symptoms of long COVID." (PMID 39720706, 2024). "IL-6 inhibitors were only approved by the Food and Drug Administration in December 2022 for the treatment of COVID-19, after our study had already concluded." (PMID 38391578, 2024). "Previous studies showed higher inflammatory markers such as procalcitonin, D-dimer, interleukin-6 and CRP resulting in a “cytokine storm” or hyperinflammatory state, which is associated with COVID-19 disease severity." (PMID 38699405, 2024). "IL-6, which is also expressed in both the acute and post-acute phase of COVID-19, induces expression of the mitochondrial fission proteins Dynamin-1-like protein and mitochondrial fission 1 protein in skeletal muscles cells and mice." (PMID 40603504, 2024). "A cohort study of COVID-19 patients showed that enhanced transcriptional activation of NF-κB produces excessive cytokines, tumor necrosis factor-α (TNF-α), and interleukin-6 (IL-6), which in turn cause severe COVID-19 morbidity." (PMID 38392902, 2024). "Elevated leptin levels have been identified in both mild and severe cases of COVID-19, and its prognostic capability has surpassed even that of traditional inflammation markers like IL-6 and CXCL-101." (PMID 39062978, 2024). "The current study showed a high prognostic value in early detection of severe illness in COVID-19 patients for both IL-6 and bio-ADM, which is consistent with the results of previous studies." (PMID 38336628, 2024). "We observed that suPAR exhibited a more pronounced additive effect on the association between BMI and COVID-19 in-hospitalization outcomes compared with CRP and IL-6." (PMID 38635301, 2024).
COVID-19 (continued). "In the case of pulmonary infections like COVID-19, serum IL-6 levels were found to rise dramatically in seriously ill individuals." (PMID 38694122, 2024). "In contrast, calprotectin levels were unrelated to IL-6 and ferritin in moderate or severe COVID-19." (PMID 39273246, 2024). "Tocilizumab, a recombinant humanized monoclonal antibody directed against the IL-6 receptor, has shown a mortality benefit in severe cases of COVID-19, underscoring the potential of IL-6 as a therapeutic target in patients with cancer and COVID-19." (PMID 39272832, 2024). "Increased cytokines are released, such as interleukin (IL-6), and various acute-phase reactants in COVID-19 can lead to endothelial injury." (PMID 40729253, 2024). "Obesity-induced chronic inflammation contributes to a proinflammatory environment characterized by elevated levels of cytokines such as interleukin (IL)-6, IL-1β, and tumor necrosis factor-alpha (TNF-α), which are implicated in the pathogenesis of COVID-19." (PMID 39861827, 2024). "The severity of COVID-19 has also been determined by serum biomarkers such as interleukin-6 (IL-6), CRP, ferritin, and lactate dehydrogenase due to their influence in the inflammatory process, leading to SARS-CoV-2 aggravation." (PMID 38687065, 2024). "The genetic studies of critical COVID-19 cases revealed that genetic variations in the IL-6 inflammatory pathway are related to fatal diseases." (PMID 39452786, 2024). "TNFα and IL-6 serve as well-established druggable cellular targets with several FDA-approved anti-TNFα or IL-6 drugs either suggested for COVID-19 treatment or in various clinical trials." (PMID 38251382, 2024). "In a Syrian hamster model with SARS-CoV-2 GFP/ΔN, the HSP90 inhibitor 17-DMAG significantly reduced COVID-19 lung injury and gene expression of TNF, IL1B and IL6, but clinical deterioration was observed (weight loss exceeding 20% body weight and ruffled fur)." (PMID 39325762, 2024). "Nonetheless, the significance of other blood markers, like C-reactive protein (CRP) and interleukin (IL)-6, in forecasting COVID-19 severity and related mortality remains essential." (PMID 39272717, 2024). "The results revealed that the predictive capacities of serum transgelin for critical cases and death were similar with COVID-19 severity scores, and obviously higher compared with IL-6 and CRP." (PMID 39676863, 2024). "Age exhibited negative correlations with levels of pro-inflammatory cytokines, including IFN-γ, TNF, IL-2, and IL-6, following COVID-19 vaccination." (PMID 38909235, 2024). "We then assessed serum IL-1β, IL-1Ra and IL-6 concentrations in COVID-19 patients according to disease severity." (PMID 39882243, 2024). "The cytokine profile of COVID-19 is characterized by elevated levels of pro-inflammatory cytokines, such as IL-6, TNF-α, IL-1β, and IFN-γ." (PMID 39130641, 2024). "Integrating variables from our prediction model for COVID-19-associated secondary invasive fungal infections, we recommend paying special attention to patients with low BMI (BMI < 28 kg/m2), elevated log IL-6 levels and fever in severe COVID-19 patients." (PMID 39040601, 2024). "More recently, IL-6 blockade has been used for the treatment of hospitalized COVID-19 and with ongoing studies blocking the IL-6 pathway to reduce cardiovascular disease in the general population." (PMID 38580710, 2024). "Since tocilizumab (IL6 inhibitor) was a possible therapy for severe COVID-19 in April–June 2020, we evaluated the Roche IL6 chemiluminescent immunoassay." (PMID 39852788, 2024). "Then, an ROC analysis of significant results was performed, and based on this, the best predictor of HAP in critical COVID-19 patients appeared to be IL-6, with an AUC = 0.810." (PMID 38391578, 2024). "We show that the plasma concentrations of the pro-inflammatory cytokines IL-6 and IL-2 are elevated in severe COVID-19 and were the primary cytokines that distinguished COVID-19 patients who died from those who survived." (PMID 39345212, 2024).